SOX2 (SRY-box transcription factor 2)
Diseases named in the same sentence as SOX2 in open-access papers (continued):
Sharing a sentence is not in itself a finding about the gene and the disease.
breast tumor (continued). "For this purpose, we purified bCSCs flow-cytometrically from primary breast tumors on the basis of the cell surface phenotype CD44+/CD24-/low and confirmed their stemness properties on the basis of the expression levels of the following markers: MRP1 and ABCG2, ALDH1, and Oct-4, Sox-2, and Nanog." (PMID 25315241, 2014). "Moreover, interaction between SOX2 and YAP/TAZ was evident in the nucleus of breast tissues, with significant increase in the interaction between YAP/SOX2 (p < 0.001) and TAZ/SOX2 (p < 0.001) in the breast tumors in comparison to their respective adjacent normal tissues." (PMID 39979255, 2025). "Moreover, we observed and calculated the number of OCT4/SOX2/NANOG/FOXP3 positive cells per area taken from sections of the tumor tissues, and consequently found similar trend in stemness genes and FOXP3 coincides with high-grade of breast tumor compared to low-grade breast tumor (p < 0.0001)." (PMID 38038865, 2023). "Furthermore, the expression of OCT4, but not PRDM14, SOX2, REX1 or NANOG was higher in breast tumor and metastasis samples, suggesting negative regulation of Xist by OCT4." (PMID 27248326, 2016).
esophageal cancer (42 papers, 2011 to 2025). A primary or metastatic malignant neoplasm involving the esophagus. "Higher expression of SOX2 and Oct4 has been reported to be associated with worse survival in some cancers, such as esophageal carcinoma." (PMID 32171280, 2020). "In the case of esophageal cancer, an elevated expression of SOX2 has been associated with enhanced proliferation and growth of ESCC tumor cells." (PMID 26370982, 2015). "It has been accepted that SOX2 expression was significantly associated with higher histological grade of esophageal carcinoma." (PMID 28983346, 2015). "In squamous lung and esophageal cancers, aberrant SOX2 expression was linked to the genomic amplification of its chromosomal location on chromosome 3q26.33." (PMID 21276239, 2011). "Previous research reports showed that the regulator of chromosome condensation 2 (RCC2) is essential for stabilization and transcriptional activation of Sox2 and its overexpression is associated with cell proliferation, migration, and tumor promotion in esophageal cancer." (PMID 40725242, 2025). "SOX2 transcription is associated with cell growth in lung and esophageal cancers." (PMID 37171044, 2023). "Similar studies in nasopharyngeal carcinoma and esophageal cancer show that PI3K/AKT signaling regulates SOX2 expression." (PMID 36118530, 2022). "AKT in nasopharyngeal carcinoma regulates the expression of the cell cycle regulator p27, which in turn modulates SOX2 expression 35, and AKT in esophageal cancer promotes overexpression of SOX2 and protects SOX2 from proteasomal degradation." (PMID 36118530, 2022). "The stem cell markers were detected by qPCR in Eca109 cells, and the results showed that overexpression of RBBP7 upregualted the expressions of esophageal cancer stem cell markers, including SOX2, KLF4, NANOG, and OCT3/4." (PMID 35538026, 2022). "Phosphorylation of SOX2 at threonine 116 stabilizes SOX2, promoting esophageal cancer cell proliferation and stemness." (PMID 35674129, 2022). "YAP was found to regulate the EMT-associated genes by inducing SOX-2 expression in cooperation with Oct-4 in NSCLC cells 12 and to directly up-regulate SOX-9 and induce stem-like properties in esophageal cancer cells." (PMID 33442415, 2021). "We found that the expression of stem cell biomarkers NANOG, OCT4, SOX2 increased in the PTX-resistant esophageal cancer cells." (PMID 34150636, 2021). "A more recent study on esophageal cancer also showed that AKT-phosphorylation promotes SOX2 stabilization by preventing its ubiquitination and degradation by UBR5." (PMID 32457900, 2020). "In esophageal cancer, SOX2 promoter hypermethylation was thought to be the main mechanism behind the silencing of SOX2 gene." (PMID 30867047, 2019). "Online analysis of TCGA data from 184 patients showed that both SOX2 and SOX2OT expressions were associated with T stage of esophagus cancers." (PMID 29849506, 2018). "Our understanding of the function of Sox2 in other malignancies is rapidly expanding, and Sox2 expression has been documented among lung, breast, hepatocellular, lung, and esophageal cancers." (PMID 23326489, 2013). "In oesophageal cancer, the expression of Oct3/4 and Sox2 proteins was reported to correlate with advanced cancer, which in turn correlated with poor clinical outcome." (PMID 22433967, 2012). "We validated the role of mSE078 and SOX2 in esophageal cancer." (PMID 37930832, 2023). "Similarly, we proved the contribution of SOX2 to cancer stemness via SOX2-enriched SE in esophageal cancer." (PMID 37930832, 2023). "The increased expression of SOX2 in esophageal cancer patients predicted a different outcome." (PMID 35382656, 2022).
esophageal cancer (continued). "Patients with early esophageal cancer could be detected with sensitive SOX2 expression signature, and then treated with surgery as soon as possible, thus affecting the overall health level of patients." (PMID 35382656, 2022). "The overexpression of SOX2 is frequently observed in the growth and propagation of tumours by clinical and experimental methods, which is currently considered as one of the main carcinogenic factors in the evolution of esophageal cancer." (PMID 35382656, 2022). "Considering that SOX2 could influence the migration and invasion capability of esophageal cancer cells and up-regulate the expression of KTN1-AS1 at transcriptional level, we then detected the influence of KTN1-AS1 on EMT related markers." (PMID 36418920, 2022). "Furthermore, we found that enhanced SOX2 expression in Eca109 cells promoted chemoresistance to cisplatin, one of the most frequently used chemotherapeutic drug for esophageal cancer, as demonstrated by a shift in the IC50." (PMID 31560173, 2019). "A previous study had reported that AKT phosphorylates SOX2 at T116 and blocks the interaction of SOX2 with UBR5, which protects SOX2 from ubiquitin-dependent protein degradation by UBR5 in human esophageal cancer." (PMID 39994220, 2025). "Consistent with the results in esophageal cancer cells, MK2206 treatment significantly enhanced the interaction UBR5 and SOX2." (PMID 39994220, 2025). "RCC2 can also upregulate and stabilize SOX2 (SRY-box transcription factor 2) expression by inhibiting ubiquitination-mediated proteasome degradation, thus facilitating the progression of esophageal cancer." (PMID 39908861, 2025). "Moreover, in terms of clinical outcomes, we found that HDAC4 expression and Sox2 expression were both negatively associated with survival in CRC, which matches a previous report that increased HDAC4 expression was associated with poor prognosis in esophageal cancer." (PMID 38473392, 2024). "UBR5 has been reported to interact with SOX2, a gene important in maintaining growth of ESC, as well as mediating proteolytic degradation via involvement of AKT in esophageal cancer." (PMID 32867711, 2020). "In this study we have used ATF technology to successfully suppress SCC in vitro and in vivo in SOX2-expressing SCC lung and esophageal cancer cells as a first step in the search for an effective treatment for SCC lung and esophageal cancers." (PMID 29262545, 2017). "In this study, we have shown both in vitro and in vivo that the targeted down-regulation of SOX2 using ATF based technologies can be used as an effective tool for the treatment of SCC in lung and esophageal cancers that express SOX2." (PMID 29262545, 2017). "Subsequently, researchers sorted out esophageal cancer stem cells from esophageal cancer cells using the SP cell sorting approach with CD44, SOX2 and Lgr5 as the markers." (PMID 28193907, 2017). "Based on the read threshold 12 for SOX2 ChIP-seq in KYSE-70 cells set by the tangent line of slope 1 in a scaled plot of SOX2 ChIP-seq read to ranked order by increasing value, we noticed that -5SE had an enriched SOX2 binding in human esophageal cancer." (PMID 37930832, 2023). "Furthermore, it was clarified that the interaction between SOX2 and UBR5 was inhibited after phosphorylation of SOX2, and thereby stabilized SOX2 in esophageal cancer." (PMID 34621737, 2021). "Although the expression of SOX2 and MKRN1 in esophageal cancer is known, studies on their correlation have not been reported yet." (PMID 37930832, 2023). "Huang D and others found that stem cell-related genes (including OCT-4, SOX-2, BMI-1, and ZFX) were upregulated in SP(side population) cells of human esophageal carcinoma 9706 cells compared with non-SP cells." (PMID 22185393, 2011).
microphthalmia (42 papers, 2007 to 2025). Congenital or developmental anomaly in which the eyeballs are abnormally small. "Sox2 is involved in crystallin regulation in murine and avian models and humans, and SOX2 mutations cause microphthalmia and cataracts." (PMID 35148715, 2022). "Several reports followed this one, describing SOX2 variants in individuals with milder ophthalmic phenotypes such as microphthalmia and uveal coloboma." (PMID 33719903, 2021). "Accordingly, a recent report has linked novel missense mutations in PAX6 (c.160A>C, p.Ser54Arg and c.372C>A, p.Asn124Lys) to severe bilateral microphthalmia, with phenotype resembling SOX2-associated MAC." (PMID 31861090, 2019). "As microphthalmia is very rarely reported in aniridia, and in some cases is thought to be caused by mutations in other important eye genes such as SOX2 and OTX2 in addition to the aniridia causing PAX6 mutation." (PMID 30258099, 2018). "Interestingly, a recent report highlights recurrent missense variants, p.S54R and p.N124K, associated with severe bilateral microphthalmia, phenocopying SOX2-associated AM." (PMID 31416264, 2019). "Mutations in SOX2 are the most common cause of bilateral anophthalmia and severe microphthalmia." (PMID 31861090, 2019). "The increase in total cell cycle time of Sox2-mutant RPCs may explain how mutations in human SOX2 contribute to microphthalmia." (PMID 25488119, 2014). "Interestingly, eye size, lens degeneration, and defective retinal morphology are frequently correlated in humans with anopthalmia/microphthalmia caused by mutations in sox2 and vsx2/chx10." (PMID 23437360, 2013). "Of these, mutations in SOX2 account for about 10% of microphthalmia, anophthalmia, and coloboma." (PMID 20057906, 2009). "Kondoh and colleagues have shown that PAX6 and SOX2 co-bind to a regulatory element driving lens induction in the chick, which suggests that lens induction failure could be responsible for microphthalmia in patients with mutations in these genes." (PMID 18039390, 2007). "Detectable retinal function may be present in microphthalmia cases, particularly those associated with SOX2 mutations." (PMID 18039390, 2007). "This includes SOX2 (OMIM #184429), in which mutations lead to syndromic microphthalmia with optic nerve hypoplasia and abnormalities of the CNS (OMIM #206900)." (PMID 39769160, 2024). "SOX2-related disorders are known to include DD, ID, ophthalmological issues like microphthalmia, brain malformations, hypogonadism, and gonadal dysgenesis." (PMID 39125556, 2024). "We next performed sequential injection of rbm24a morpholino and exogenous sox2 RNA to determine the extent to which sox2 can suppress the rbm24a-depleted microphthalmia." (PMID 33494192, 2021). "Analysis of eye development in Sox2 hypomorphic mice indicated variable degrees of microphthalmia attributed to abnormal neural progenitor proliferation, consistent with findings in human." (PMID 25111779, 2014). "The clinical presentation of patient 9 did not encompass microphthalmia, which is typically associated with SOX2-related diseases." (PMID 39125556, 2024). "The rbm24a knockdown embryos displayed more embryos with microphthalmia or microphthalmia with cardiac edema when compared to the rbm24a knockdown with sox2 RNA, indicating that injection of exogenous sox2 RNA can partially suppress the rbm24a knockdown phenotype." (PMID 33494192, 2021). "Our data indicate sox2 is a main contributor to the rbm24a-induced microphthalmia." (PMID 33494192, 2021). "From this, we hypothesized that knockdown of rbm24a with the addition of exogenous sox2 would suppress the microphthalmia phenotype." (PMID 33494192, 2021). "Mutations in several genes have been reported in patients with microphthalmia and/or coloboma, including BMP4 (OMIM 112262), VSX2 (CHX10; OMIM 142993), CRYBA4 (OMIM 123631), OTX2 (OMIM 600037), RAX (OMIM 601881), SIX6 (OMIM 606326), and SOX2 (OMIM 184429)." (PMID 20057906, 2009).
microphthalmia (continued). "Indeed, in a previous report, successful fertility induction in a SOX2 heterozygous IHH woman without severe ocular disease resulted in a child who was born with bilateral microphthalmia." (PMID 36602867, 2023). "There were no apparent phenotypic manifestations of SOX2-related microphthalmia in the mother." (PMID 33719903, 2021).
liver cancer (39 papers, 2015 to 2025). An epithelial or non-epithelial malignant neoplasm that arises from the liver. "Research has shown that SOX2 expression is strongly linked to liver cancer metastasis and patient prognosis." (PMID 41425729, 2025). "Later, studies reported that NP treatment disrupted the spherical formation of cancer stem cells, which is the cause of metastasis in liver cancer, and by reducing the expression of stem cell genes such as SOX2, BMI-1, Nanog, and c-Myc." (PMID 39356934, 2024). "Subsequent studies reported that NP treatment disrupts the spherical formation of cancer stem cells, which are the cause of metastasis in liver cancer, and reduces stem cell markers such as SOX2, BMI-1, Nanog and c-Myc by inhibiting stem cell genes." (PMID 39459502, 2024). "In addition, overexpression of SOX2, a biomarker of putative CSCs, causes the durability of liver cancer cells and promotes HCC progression, and thereby decreases patient survival." (PMID 34436030, 2021). "Further analysis using RT quantitative PCR (qPCR) revealed that the expression of the pluripotent transcription factors OCT4, NANOG, and SOX2 was significantly higher in both the human PSCs than in a somatic liver cancer cell line (HepG2215)." (PMID 39040044, 2024). "Sirtuin 1 (SIRT1) is overexpressed in liver cancer and acts as a tumor promoter through deacetylation by sex-determining region Y-box 2 (SOX2)." (PMID 39281271, 2024). "Schlegel reported that conditioned medium extracted from mouse fibroblasts increased the expression of stemness genes, including Sox2, Oct4, Nanog, and Klf4, in liver cancer cells." (PMID 36348351, 2022). "A study showed that C7 had increased expressed in liver cancer stem cells and enhanced the stemness of liver cancer cells by up-regulating Nanog, Oct4, Sox2, and C-myc." (PMID 35111412, 2022). "Our findings indicated that SIRT1 and SOX2 were upregulated in human liver cancer tissue sections compared to the adjacent tissue." (PMID 35674129, 2022). "Liver cancer cells with stem cell phenotypes generally highly express well-known stem cell-related molecular markers, such as Oct-4, Sox-2, Nanog, Epithelial cell adhesion molecule (EpCAM), CD90, CD133, and CD44." (PMID 31185668, 2019). "Liver cancer cells can be reprogrammed into induced cancer stem cells (iCSCs) by exogenous expression of the reprogramming transcription factors Oct4, Sox2, Klf4 and c-Myc (OSKM)." (PMID 27894081, 2017). "Importantly, Napabucasin treatment impaired spheroid formation of liver cancer stem cells and downregulated the expression of stemness genes such as SOX2, BMI-1, Nanog, and c-Myc." (PMID 38326371, 2024). "In addition, ALDH2 promotes the expression of cancer stem biomarkers (e.g., Nanog, Oct4, and Sox2), leading to the proliferation, migration, and invasion of liver cancer stem cells (LCSCs)." (PMID 35477569, 2022). "SIRT1 is overexpressed in liver cancer and acts as a tumor promoter via SOX2 deacetylation." (PMID 35674129, 2022). "Importantly, Napabucasin treatment impairs spheroid formation of liver cancer stem cells and downregulates the expression of stemness genes such as SOX2, BMI-1, Nanog, and c-Myc." (PMID 31277685, 2019). "Moreover, SIRT1 induces expression of the transcription factor SOX2 to stimulate the self-renewal of liver cancer stem cells." (PMID 28881735, 2017). "Moreover, SIRT1 regulates the transcription of SOX2 through DNA methylation, leading to hypermethylation of the SOX2 promoter, which affects the self-renewal and tumorigenicity of liver cancer stem cells (CSCs), highlighting SIRT1’s vital role in cancer progression." (PMID 40052151, 2025). "In the context of hepatic cancer, TGF-β promotes tumor development through a newly identified H19 long noncoding RNA signaling axis via SRY (sex determining region Y)-box 2 [SOX2]." (PMID 40260391, 2025). "SOX2 activates cell invasion and epithelial-mesenchymal transition (EMT) by regulating the expression of Slug in liver cancer cells." (PMID 41425729, 2025).
liver cancer (continued). "We also found that Dicer expression was inversely correlated with SOX2 and OCT4 expression in liver cancer tissues." (PMID 35253323, 2022). "SOX2 is a main downstream regulator of SIRT1‐mediated self‐renewal and tumorigenic potential of liver cancer stem cells, and SOX2 is amplified and drives proliferation in small-cell lung cancer." (PMID 32055024, 2020). "The expression of SOX2 and NANOG, 2 key stem cell biomarkers regulating cell self‐renewal, further verified the role of SHH/Gli signalling in CD90+ liver cancer stem cell regulation in this study." (PMID 29722127, 2018). "In this study, we first established C3A-derived liver cancer stem cells by OSKM method [OCT4, SOX2, KLF4, and c-MYC], termed C3A-induced cancer stem cells (C3A-iCSCs) which acquired self-renewal and stemness abilities." (PMID 26540347, 2015). "In liver cancer cells, CAP treatment downregulated the expression of silent information regulator 1 (SIRT1), resulting in reduced SOX2 deacetylation, thereby reducing the stability of SOX2 and leading to the transfer of SOX2 from the nucleus to the cytoplasm." (PMID 40362978, 2025). "3- CAMKIIG may increase hepatic cancer stemness characteristics by inducing the expression of MYC in β-catenin dependent manner and stemness markers, Oct4 and SOX2, expression via induction of AKT phosphorylation." (PMID 30944375, 2019). "Furthermore, the expression of Sex Determining Region Y‐Box 2 (SOX2), the self‐renewal regulatory factors and major stem cell markers, was also greatly repressed by CD90 depletion in liver cancer cells." (PMID 29722127, 2018). "Pluripotency genes, such as Oct4, Sox2 and Nanog, were however down‐regulated in SMC‐treated samples, indicating that the differentiated liver cancer cells did not possess stemness properties." (PMID 35343115, 2022).